RTEL1 (regulator of telomere elongation helicase 1)
Description:
A probable ATP-dependent DNA helicase implicated in telomere-length regulation, DNA repair and the maintenance of genomic stability. Acts as an anti-recombinase to counteract toxic recombination and limit crossover during meiosis. Regulates meiotic recombination and crossover homeostasis by physically dissociating strand invasion events and thereby promotes noncrossover repair by meiotic synthesis dependent strand annealing (SDSA) as well as disassembly of D loop recombination intermediates. Also disassembles T loops and prevents telomere fragility by counteracting telomeric G4-DNA structures, which together ensure the dynamics and stability of the telomere.
Synonyms: C20orf41; KIAA1088; NHL; bK3184A7.3; DKFZP434C013; RTEL; DKCA4; DKCB5; PFBMFT3
Tractability: PROTAC: ubiquitination databases record sites on it.
Gene: Protein-coding gene on chromosome 20 (63,657,810 to 63,696,253, forward strand). Ensembl gene ENSG00000258366.
Subcellular location: Nucleus
Subcellular location (Human Protein Atlas): Nuclear speckles; Nuclear membrane; Nucleoplasm
Pathways (Reactome):
Cell Cycle: Telomere Extension By Telomerase
DNA Repair: Resolution of D-loop Structures through Synthesis-Dependent Strand Annealing (SDSA)
Metabolism: Cytosolic iron-sulfur cluster assembly
Gene Ontology:
Molecular function: ATP binding; ATP hydrolysis activity; DNA helicase activity; protein binding; DNA polymerase binding; 4 iron, 4 sulfur cluster binding; DNA binding; helicase activity; hydrolase activity, acting on acid anhydrides, in phosphorus-containing anhydrides; metal ion binding; nucleic acid binding
Biological process: negative regulation of t-circle formation; positive regulation of telomere capping; positive regulation of telomere maintenance via telomere lengthening; regulation of double-strand break repair via homologous recombination; telomere maintenance; telomeric loop disassembly; DNA strand displacement; mitotic telomere maintenance via semi-conservative replication; negative regulation of DNA recombination; negative regulation of telomere maintenance in response to DNA damage; positive regulation of telomere maintenance; positive regulation of telomeric loop disassembly; replication fork processing; telomere maintenance in response to DNA damage; DNA recombination; DNA repair; DNA replication; regulation of cellular response to stress; regulation of DNA recombination
Cellular component: nuclear membrane; nuclear speck; nucleoplasm; nucleus; chromosome, telomeric region
Genetic constraint (gnomAD): Loss-of-function variants: 89 observed, 160.7 expected, observed/expected ratio (o/e) 0.55, 90% interval 0.47 to 0.66. The synonymous counts are far from expectation, so gnomAD's model fits this gene poorly and the ratio says little. Missense variants: 1,941 observed, 1,759.6 expected, observed/expected ratio (o/e) 1.1, 90% interval 1.06 to 1.14. Synonymous variants: 958 observed, 729.58 expected, observed/expected ratio (o/e) 1.31, 90% interval 1.24 to 1.38.
Gene-disease validity (ClinGen):
ClinGen rates the evidence that RTEL1 causes each of these diseases.
pulmonary fibrosis and/or bone marrow failure, Telomere-related, 3 (semidominant): Definitive. Any pulmonary fibrosis and/or bone marrow failure, Telomere-related in which the cause of the disease is a mutation in the RTEL1 gene.
Homologues: Orthologues: chimpanzee RTEL1 (95% identical), macaque RTEL1 (91% identical), pig RTEL1 (76% identical), dog RTEL1 (75% identical), rat Rtel1 (74% identical), guinea pig RTEL1 (72% identical), mouse Rtel1 (70% identical), tropical clawed frog rtel1 (53% identical), zebrafish rtel1 (48% identical), Drosophila melanogaster Rtel1 (29% identical), Caenorhabditis elegans rtel-1 (24% identical). Paralogues in human: BRIP1 (22% identical), DDX11 (16% identical), ERCC2 (15% identical).
Diseases named in the same sentence as RTEL1 in open-access papers:
RTEL1 is named in the same sentence as 115 diseases in open-access papers, as found by Europe PMC text mining. Sharing a sentence is not in itself a finding about the gene and the disease. The quoted sentences say what the papers report.
glioma (44 papers, 2010 to 2025). A benign or malignant brain and spinal cord tumor that arises from glial cells (astrocytes, oligodendrocytes, ependymal cells). "RTEL1 is linked with telomere length which has been previously implicated in observational and MR studies to have an association with glioma risk." (PMID 39565278, 2025). "The mutation in the RTEL1 gene has been linked to a variety of human diseases, including dyskeratosis congenita (DC), Hoyeraal-Hreidarsson syndrome, glioma (HHS), glioblastoma, pulmonary fibrosis, bone marrow failure, breast cancer, and other malignancies." (PMID 39240887, 2024). "Rtel1 gene amplification has been observed in gastrointestinal cancer and adrenocortical carcinoma and Rtel1 single‐nucleotide polymorphisms have been associated with increased susceptibility to glioma underlying a key role for RTEL1 in cancer development." (PMID 39180489, 2024). "A GWAS study identified two SNPs within intron 12 (rs6010620) and intron 17 (rs4809324) of RTEL1 that are significantly associated with glioma and astrocytoma predisposition." (PMID 38532312, 2024). "In this study, by a series of in vitro and in vivo assays, we are going to investigate the relationship between RTEL1 expression and clinicopathological characteristics in glioma patients, and to explore the mechanisms of RTEL1 caused in glioma tumorigenesis." (PMID 38532312, 2024). "And a GWAS study of 1878 cases and 3670 healthy controls from four countries identified a significant association between the RTEL1 gene rs6010620 polymorphism and glioma risk." (PMID 38532312, 2024). "Studies have shown that the RTEL1 genomic locus is often amplified in human cancers and the polymorphisms of this gene are associated with several cancers, including gliomas, neuroblastoma, lung, and breast cancer." (PMID 39240887, 2024). "Another study of 692 adult glioma cases and 3992 controls reported that two SNPs rs6010620 and rs4809324 of RTEL1 were significantly associated with the susceptibility to gliomas and astrocytomas." (PMID 38532312, 2024). "RTEL1 has been implicated in a number of genetic diseases and cancer development, including glioma, breast, lung and gastrointestinal tumors." (PMID 39180489, 2024). "Changes in the activity of an enhancer on 20q13.33 led to abnormal expression of multiple genes associated with glioma risk (e.g., RTEL1, RTEL1-TNFRSF6B, SRMS and GMEB2)." (PMID 37349788, 2023). "A functional SNP on the 20q13.33 region in linkage disequilibrium with another SNP mapped to intron 14 of RTEL1 affects the activity of an enhancer on 20q13.33 that leads to modulated expression of multiple genes implicated in glioma risks, including RTEL1." (PMID 36253342, 2023). "A meta-analysis showed a correlation between the G allele of RTEL1 rs6010620 and an increased risk of glioma, including 1878 cases and 3670 controls." (PMID 38001404, 2023). "Single nucleotide polymorphisms (SNPs) of RTEL1 associated with glioma are mostly found in non‐coding (intronic) regions of the gene." (PMID 36253342, 2023). "Three of these glioma-associated SNPs were pleiotropic: RTEL1 (rs1291209: allergic disease asthma hay fever or eczema), CDKN2B (rs6475604: coronary heart disease, glaucoma, vertical cup disc ratio), and PHLDA1 (rs1565765: atrial fibrillation)." (PMID 33495464, 2021). "Variants of RTEL1 is associated with molecular subtype in IDH wild-type gliomas (32386320, 31842352)." (PMID 34568059, 2021). "Of interest, RTEL1 and the read-through transcript RTEL1-TNFRSF6B had been postulated to be target genes in 20q13.33 due to its role in telomere maintenance and also the fact that the top glioma GWAS risk allele resides within an intron of RTEL1 (rs2297440)." (PMID 33936159, 2021). "For example, high-grade gliomas are associated with risk variants in RTEL1, CDKN2B, and TERT, while low-grade gliomas with IDH mutation-1p/19q codeletion are associated with risk variants in CCDC26 and PHLDB1 regions." (PMID 31968687, 2020).
glioma (continued). "Recently, genome‐wide association studies (GWAS) have shown that RTEL1 dysfunction appears to be closely related to certain cancers and age‐related diseases such as lung cancer, glioma, astrocytoma, stroke, and colorectal cancer." (PMID 30623606, 2019). "This study provides a deeper understanding of relationships between RTEL1 variants and risk of glioma." (PMID 30462709, 2018). "In case-control studies for glioma, the associations were detected for the intronic SNPs (rs6010620 and rs2297440) of RTEL1 in the United States (US) and Han Chinese populations." (PMID 30462709, 2018). "A number of GWASs and candidate gene studies have identified RTEL1 variants involved with genetic predispositions to glioma development." (PMID 30462709, 2018). "Previous studies have identified multiple loci for inherited susceptibility to glioma development, including the regulator of telomere elongation helicase 1 (RTEL1)." (PMID 30462709, 2018). "Of the extensively investigated RTEL1 SNPs, the intronic rs6010620 was the most studied SNP in White and Chinese populations, although there were differences in the effect of this SNP on glioma risk." (PMID 30462709, 2018). "Despite these limitations, the present study reinforces understanding of RTEL1 association with adult gliomas in Korean populations." (PMID 30462709, 2018). "This study demonstrates that previously identified loci in RTEL1 are confirmed to have an association with increased risk of adult gliomas." (PMID 30462709, 2018). "The single nucleotide polymorphism (SNP) of RTEL1 gene has been confirmed to be associated with telomere-related diseases such as Hoyeraal Hreidarsson Syndrome, glioma, lung cancer and atopic dermatitis." (PMID 29383136, 2017). "Regulator of telomere elongation helicase 1 (RTEL1) rs6010620 polymorphism was likely to be associated with increased glioma risk." (PMID 26249370, 2015). "This suggests that additional LTL-associated SNPs outside the TERC, TERT and RTEL1 regions also confer glioma risk." (PMID 26646793, 2015). "Haplotype “GCT” in RTEL1 gene was found to be associated with risk of glioma (OR, 0.7; 95% CI, 0.57-0.86; Fisher’s P = 0.0005; Pearson’s P = 0.0005)." (PMID 23683922, 2013). "In this case–control study in Han Chinese population, we found two susceptibility tSNPs in RTEL1 gene that were associated with increased risk of glioma (rs6010620 and rs2297440)." (PMID 23683922, 2013). "Four tSNPs were detected to be associated with glioma by model association analyses including rs6010620 and rs2297440 in the RTEL1 gene, rs12022378 in the DCLRE1B gene, and rs12917 in the MGMT gene." (PMID 23683922, 2013). "And, we will also investigate the association between germline RTEL1 variants and somatic RTEL1 mutations, and the relationship between serum RTEL1 expression and somatic RTEL1 expression in the same glioma subjects." (PMID 23683922, 2013). "We observed two tSNPs in RTEL1 gene to be associated with the risk of glioma by recessive model (rs6010620, OR, 2.09; 95% CI, 1.39-3.13; P = 0.0004, and rs2297440, OR, 2.02; 95% CI, 1.35-3.04; P = 0.0007)." (PMID 23683922, 2013). "Two significant tSNPs in RTEL1 gene were observed to be associated with glioma risk (rs6010620, P = 0.0016, OR: 1.32, 95% CI: 1.11-1.56; rs2297440, P = 0.001, OR: 1.33, 95% CI: 1.12-1.58) by χ2 test." (PMID 23683922, 2013). "Two significant tSNPs in the RTEL1 gene were observed to be associated with glioma risk at a 5% level (rs6010620, P = 0.0016, OR: 1.32, 95% CI: 1.11-1.56; rs2297440, P = 0.001, OR: 1.33, 95% CI: 1.12-1.58) by χ2 test." (PMID 23683922, 2013). "They identified five risk loci for glioma including rs6010620 intronic to RTEL1 gene (P = 2.52 × 10-12) to be associated with glioma risk." (PMID 23683922, 2013).
glioma (continued). "RTEL1 has previously been identified as a risk factor for glioma, and studies have tried to identify whether telomere length has an established causative effect on the risk of glioma, although no definitive conclusion has been reached." (PMID 39565278, 2025). "Long RTL remained closely associated with recurrence (OR = 1.70, 95% CI = 1.00-2.89, p < 0.05), and higher level of RTEL1 mRNA also associated with gender (OR = 2.23, 95% CI = 1.77–3.24, p = 0.012) and pathological diagnosis (OR = 3.19, 95% CI = 1.15–5.22, p = 0.002) in glioma patients." (PMID 38532312, 2024). "In addition to pulmonary fibrosis, it was shown that other RTEL1 variants (e.g., rs2297440) increase risk of glioma and astrocytoma." (PMID 38653581, 2024). "It is assumed that the RTEL1 polymorphism may change the binding affinity of transcription factors, leading to telomere elongation dysfunction, thus affecting the survival of glioma cells." (PMID 38001404, 2023). "Several RTEL1 mutants are also associated with an increased risk of glioma." (PMID 36253342, 2023). "RTEL1, an ATP-dependent DNA helicase, was reported as a risk gene for glioma." (PMID 34568059, 2021). "Second, variants in CDKN2B-AS1, EGFR, and RTEL1 were associated with IDH-wildtype glioma." (PMID 31842352, 2019). "However, in the past decade, RTEL1 variants have been associated with the decreased risk of several brain cancers and age‐related disease including glioma, astrocytoma, glioblastomas, and congenital dyskeratosis." (PMID 30623606, 2019). "Therefore, we analyzed the selected RTEL1 SNPs, including previous glioma variants, for association with risk of adult gliomas in Korean populations." (PMID 30462709, 2018). "Therefore, we sought to comprehensively examine the genetic interaction between RTEL1 variants and risk of glioma with respect to defined histological and molecular subtypes." (PMID 30462709, 2018). "Independent association signals among glioma-associated RTEL1 variants." (PMID 30462709, 2018). "In addition, we used general PCs matched for age and sex to estimate the impact of the association between RTEL1 variants and risk of adult gliomas." (PMID 30462709, 2018). "In addition, 13 RTEL1 SNPs were found to have significant associations with risk of adult gliomas in Korean populations." (PMID 30462709, 2018). "Some RTEL1 variants may lead to a higher risk for glioma development." (PMID 34568059, 2021). "However, the association between RTEL1 variants and risk of glioma has not been well understood." (PMID 30462709, 2018). "In previous genome-wide association studies, researchers have shown that genetic polymorphisms in the telomere-related genes TERC, TERT and RTEL1 are related to increased glioma susceptibility, suggesting that telomere may play an important role in glioma genesis." (PMID 27655710, 2016). "Further study using RNA sequence and phospho-specific antibody microarray assays identified JNK/ELK1 signaling was up-regulated by RTEL1 in glioma cells through ROS." (PMID 38532312, 2024). "Second, knocking down of RTEL1 in glioma cells showed significant growth-inhibitory effect by inhibition of cell proliferation, colony formation, migration, invasion, and tumorigenic potential in nude mice, and induction of cell cycle arrest and apoptosis." (PMID 38532312, 2024). "Similarly, two further glioma GWAS studies, revealed a significant association with SNP (rs6010620) in intron 12 of the RTEL1 gene, and amplification of the 20q13.33 region was observed in nearly 30% of gliomas, with copy-number changes correlating with RTEL1 expression levels." (PMID 38532312, 2024). "Both telomere length and RTEL1 mRNA in gliomas is significantly elevated compared to those in the meningoma control tissues." (PMID 38532312, 2024). "By comparing differentially expressed genes in the two glioma cell lines, we identified 1131 genes which are regulated by RTEL1 in both cell lines." (PMID 38532312, 2024).
glioma (continued). "In order to exlpore the role of RTEL1 in gliomas, we first tested relative telomere length (RTL) and RTEL1 mRNA in gliomas and non-glioma control samples by using quantitative real-time RT-PCR (qRT-PCR)." (PMID 38532312, 2024). "Relative telomere length (RTL) and RTEL1 mRNA was explored and regression analysis was performed to further examine the relationship of the RTL and the expression of RTEL1 with clinicopathological characteristics of glioma patients." (PMID 38532312, 2024). "In conclusion, our study indicated that RTEL1 mRNA expression was positive correlation with telomere length and predicates worse progression in glioma patients." (PMID 38532312, 2024). "In this study, we provided strong evidences supporting that RTEL1 is a potent oncogene in glioma both in vitro and in vivo." (PMID 38532312, 2024). "Further in vitro studies demonstrate that RTEL1 promoted proliferation, formation, migration and invasion ability of glioma cells." (PMID 38532312, 2024). "When we exclude patients carried TERT promoter mutations, a significant difference was found between high and low level of RTEL1 mRNA groups in 238 glioma patients (p < 0.05)." (PMID 38532312, 2024). "We observed that high expression of RTEL1 is positively correlated with telomere length in glioma tissue, and serve as a poor prognostic factor in TERT wild-type patients." (PMID 38532312, 2024). "The genomic 20q13.33 region including RTEL1 was found to be amplified in nearly 30% of gliomas with copy number change correlating with RTEL1 expression." (PMID 36253342, 2023). "Recently, GWAS showed that RTEL1 gene variations seem to be closely related to various diseases, such as glioma, lung cancer, astrocytomatal cancer, coronary heart, interstitial pneumonia, and ulcerative colitis." (PMID 38001404, 2023). "Another study suggested that over‐expression of RTEL1 overcomes the tumor‐suppressive effects of microRNA 4530 (miRNA‐4530) in human gliomas, and inversely, miRNA‐4530 over‐expression inhibits the malignant biological behaviors of human glioma cells." (PMID 36253342, 2023). "The only GWAS of glioma in an East Asian population confirmed associations near TERT, PHLDB1 and RTEL1, and identified two new variants [32•]." (PMID 34817716, 2021). "We further show that this SNP affects glioma risk potentially through the altered expression of STMN3, RTEL1, GMEB2, and several other genes based on CRISPR deletion of the risk enhancer." (PMID 33169458, 2021). "Variants in CDKN2B and RTEL1 are strongly associated with high-grade glioma while variants in CCDC26 and PHLDB1 are associated with low-grade glioma." (PMID 26839018, 2016). "We also observed in the RTEL1 gene a haplotype “GCT” that was associated with a decreased the risk and a haplotype of “ATT” with an increased risk of developing glioma." (PMID 23683922, 2013). "Two single variants, the genotypes of “GG” of rs6010620 and “CC” of rs2297440 (rs6010620 and rs2297440) in the RTEL1 gene, together with two haplotypes of GCT and ATT, were identified to be associated with glioma development." (PMID 23683922, 2013). "For three genes (HEATR3, PHLDB1 and RTEL1) there were both expression and splicing causal effects on glioma risk, and for one gene (EGFR) there were both expression and protein abundance causal effects on glioma risk)." (PMID 39565278, 2025). "However, the expression of RTEL1 in gliomas and its role in human cancers including glioma remains totally unclear." (PMID 38532312, 2024). "We also found that RTEL1 might promote glioma tumorigenesis through JNK/ELK1 cascade and ROS signaling." (PMID 38532312, 2024). "First, we demonstrated that RTEL1 was frequently up-regulated in gliomas compared to matched non-cancerous tissues, and found the association of increased expression of RTEL1 with poor patient outcomes." (PMID 38532312, 2024). "In addition, we also evaluated the effect of RTEL1 knockdown on glioma cell cycle distributions and apoptosis." (PMID 38532312, 2024).